DLL4 (delta like canonical Notch ligand 4)
Diseases named in the same sentence as DLL4 in open-access papers (continued):
Sharing a sentence is not in itself a finding about the gene and the disease.
tumor (continued). "In addition, Dll4 overexpression was expected to promote vessel maturation and stabilize the tumour vasculature by reducing its remodeling capacity and, in this way, the risk of development of therapy resistance and also improve tumor drug delivery." (PMID 28288569, 2017). "The stronger inhibitory effect on tumor cell proliferation through Dll4 ubiquitous deletion may have therefore prevented the accumulation of more mutations that lead to tumor initiation, promote the transition of microadenomas to macroadenomas and favor the neoplastic transformation." (PMID 28086833, 2017). "Together our results demonstrate that the salt-and-pepper differential pattern of Dll4 expression normally associated with vascular branching switches to synchronized fluctuations under conditions of experimental high Vegfa, in retinopathy and tumour angiogenesis." (PMID 27074663, 2016). "In addition, Dll4 blockade causes a significant tumour growth delay in various tumour cell lines." (PMID 24736631, 2014). "Addition of exogeneous DLL4 resulted in enhanced tumor cell numbers via Notch2 and/or Notch3-mediated canonical pathway activation." (PMID 39951484, 2025). "Inhibition of DLL-4 signaling induces uncontrollable vessel sprouting and creates a dense but nonfunctional angiogenic network, which reduces tumor growth and increases tumor hypoxia." (PMID 40003637, 2025). "In vivo experiments verified DLL4 downregulation inhibited 4T1-TTN-MUT subcutaneous tumor proliferation and promoted apoptosis." (PMID 41326912, 2025). "CytoTRACE analysis also displayed that DLL4+ cells were a subpopulation of malignant tumor cells with relatively high stemness features." (PMID 41326912, 2025). "To date, some researches have demonstrated that IFN-γ can inhibit tumor angiogenesis by downregulating integrin αVβ3, Dll4, Dll1, and vascular endothelial growth factor A (VEGF-A)." (PMID 40370455, 2025). "DLL4 stimulation resulted in canonical Notch pathway activation and increased tumor cell viability and proliferation in RT-4, 647-V, T-24 and KU-19-19 cells." (PMID 39951484, 2025). "DLL4 or MCT4 blockade significantly limited tumor burden and proliferation compared with Nab-PTX + pembrolizumab alone." (PMID 41326912, 2025). "Dll4 blockade also reduces endothelial proliferation and tumor angiogenesis in various tumor models." (PMID 40299408, 2025). "A higher proportion of DLL4+ subpopulations predicted more metastasis, advanced clinical staging, and higher tumor proliferation index." (PMID 41326912, 2025). "Multiplex IHC staining showed that DLL4 and EpCAM were co-localized in tumor cells with low expression of TTN." (PMID 41326912, 2025). "Particularly, DLL4 expression correlates closely with vascular density in tumors; its inhibition can reduce the formation of functional vessels, thereby suppressing tumor vascular supply and growth." (PMID 40486870, 2025). "The findings indicated that TTN inactivation promotes tumor immune evasion in TNBC by activating the DLL4-NOTCH2-MCT4 signaling axis." (PMID 41326912, 2025). "Systematic MDSC depletion by Gr-1 antibody in vivo attenuated tumor growth differences between DLL4-vector and DLL4-OE groups." (PMID 41326912, 2025). "From a therapeutic perspective, blocking DLL4 signaling is akin to cutting off the tumor blood supply, thereby inhibiting tumor growth." (PMID 40486870, 2025). "Inhibition of Notch/Dll4 signaling with secretase inhibitors (DesOH LY-411575) leads to inflated but often unproductive angiogenesis in murine tumor models." (PMID 38678014, 2024). "In this study, authors showed the presence of the Notch ligand DLL4 in EVs released by both endothelial cells and tumor cells overexpressing DLL4." (PMID 39697631, 2024). "In preclinical cancer models, it has been demonstrated that DLL4-Fc, a recombinant protein that mimics the binding of Delta-like ligand 4 (DLL4), activates Notch signaling and inhibits tumor development." (PMID 38791461, 2024).
tumor (continued). "Overall, these investigations showed that As2O3’s anti-tumor effect is mediated via its anti-angiogenesis activity involving the inhibition of Dll4-Notch and VEGF signaling networks in both NSCLC and SCLC." (PMID 39717738, 2024). "This occurs via TNF-α-induced expression of endothelial cell-specific molecule-1 (ESM1), which regulates matrix metalloproteinase 9, VEGF, and delta like canonical Notch ligand 4 (DLL4), thereby contributing to tumor metastasis." (PMID 39337337, 2024). "It was found that DLL4 was highly expressed in tumor vasculature and blocking DLL4 signaling with a soluble form of DLL4 inhibited tumor angiogenesis and growth." (PMID 38791461, 2024). "An anti-DLL4 mAb in colorectal tumor-bearing mice inhibited tumor cell proliferation and reduced tumor volume." (PMID 38254219, 2024). "It has previously been shown that DLL4/Notch1 inhibition increases vascularization, leading to unproductive angiogenesis that inhibits tumor growth." (PMID 39095583, 2024). "The combined treatment of CTX-009 and irinotecan on SW48 and SW620 xenograft mice showed a synergistic effect, and their combination reduced the expression of DLL4 in tumor tissue and promoted the apoptosis of tumor cells." (PMID 38254219, 2024). "Enoticumab (REGN421) is an anti-DLL4 mAb that displayed modest anti-tumor activity in phase I clinical trials (NCT00871559) for patients with solid tumors, with 50% of patients having SD, and 2 out of 32 achieving PR." (PMID 38612911, 2024). "In a study published in 2006, the role of DLL4 in tumor angiogenesis was investigated using preclinical models." (PMID 38791461, 2024). "We demonstrate that robust ML methods can identify the alterations in host Dll4 expression from the tumor dynamic imaging datasets, and thus these methods can potentially stratify patients for Dll4 targeted therapies." (PMID 36900252, 2023). "Dll4 is overexpressed in various types of cancer, including breast, ovarian, and colorectal cancer, and has been shown to promote tumor angiogenesis, growth, and metastasis by interacting with receptors on endothelial cells (ECs)." (PMID 36900252, 2023). "In patient-derived xenograft models of colorectal cancer and T-ALL, the expression of Notch ligand DLL4 in endothelial cells was reported to facilitate an escape from dormancy and metastatic colonization by activating Notch3 signaling in tumor cells." (PMID 37887354, 2023). "Treatment with an anti-DLL4 neutralizing antibody or the silencing of Notch3 in tumor cells had marked pro-apoptotic, anti-proliferation, and reduced tumor burden in vivo." (PMID 37887354, 2023). "The authors further identified a paracrine signaling between EC-expressing Dll4 and adjacent tumor cell-expressing Notch1, whose inhibition led to increased angiogenesis, with reduced vascular perfusions and demonstrated a potent anti-tumor effect." (PMID 38269089, 2023). "HIF­1α-induced basic fibroblast growth factor and VEGF were reported to play a synergistic role in the regulation of Dll4 in tumor cells." (PMID 36798826, 2023). "The expression of Notch ligand Dll4 was much higher in the endothelium of tumor blood vessels compared to nearby normal blood vessels, indicating that Notch signaling were implicated in tumor angiogenesis." (PMID 36798826, 2023). "Numerous investigations have reported that interventions in the Dll4-Notch signaling pathway lead to tumor growth inhibition." (PMID 37292204, 2023). "It has been described a dual role for the Notch receptor (Notch 1–4)-ligand (JAG1, JAG2, DLL1, DLL3 and DLL4) pathways as oncogenic or tumor suppressors." (PMID 36745330, 2023). "The expression of Dll4 depends on continuous VEGF signaling, but blockage of the VEGF signaling pathway causes a rapid and marked decrease in the expression of Dll4 in the tumor vessels." (PMID 36910471, 2023). "This suggests that high levels of Dll4 in DCs indicate the high anti-tumor potential because of upregulated antigen presentation and adaptive immune responses." (PMID 37131214, 2023).
tumor (continued). "Expressions of Btg2 and Dll4, previously studied as tumor suppressors, were upregulated in the Vactosertib and T1-44 combination treatment group." (PMID 36765032, 2023). "The Dll4-Notch-hey2 pathway is a critical negative regulator of tumor angiogenesis, restraining excessive VEGF-induced vascular sprouting and angiogenesis." (PMID 36910471, 2023). "In a mouse tumor model, a soluble form of DLL4 (D4ECD-Fc) blocked tumor growth by interfering with vascular function despite increased tumor vessel density." (PMID 36834869, 2023). "The role of DLL4/Notch1 signaling in the development of the tumor vasculature has been studied extensively where it has been shown that Tip Cell formation, the initial cellular step of angiogenesis, is inhibited by DLL4–Notch signaling." (PMID 36376768, 2023). "Analysis of several malignant tissues reveal the enhanced expression of DLL4 in RCC due to increasing invasion grade and is found to be associated with tumor size, clinical stage, and lymph node metastasis." (PMID 37970211, 2023). "Simultaneous infection of stromal and tumor cells; Upregulation of Fez1 and Pycard; Downregulation of DLL-4, Angiopoietin 2, PECAM, Tie-1, and FOS EGR2, CREB-5, IL-6, Map2K1, CCL22, TIMD4 and CCL19." (PMID 35640930, 2022). "In specific, aiming mouse Dll4 in xenograft models decreased the activity of Notch in malignant tumor cells." (PMID 35406423, 2022). "Hepatocyte-specific Dll4 knockout abolishes the Notch1 signaling and suppresses the tumor progression." (PMID 35064244, 2022). "In human tumors, DLL4 expression was thought to be restricted to the tumor vasculature, and its expression appeared to correlate with the clinical outcome in a panel of tumors, such as breast, ovarian, gastric and resected pancreatic tumors 95-98." (PMID 35673577, 2022). "The aim of this review is to summarize the latest details considering the role of Dll4 in cancer, since recent data report that Dll4 has a major key role in tumor angiogenesis." (PMID 35406423, 2022). "In gastric CSCs, an abundance of Delta-like ligand 4 (DLL-4) promotes tumor angiogenesis and metastasis." (PMID 35800881, 2022). "When DLL4 is inhibited, small blood vessel branches sprout, tumor vascular density increases, vascular function remains poor, overall tumor perfusion decreases, and tumor growth is inhibited." (PMID 35332121, 2022). "More importantly, recent reports have found that DLL4/Notch signaling is the most significant of all the signaling pathways involved in tumor angiogenesis." (PMID 35846998, 2022). "Other studies have also reported that Dll4 blockage is correlated to inhibition of tumor growth including ovarian, gastric and lung cancer." (PMID 35406423, 2022). "DLL4/Notch/Heyl/matrix metalloproteinase (MMP)-9 cascades promote the distant metastasis of the tumor, and lentivirus short hairpin RNA (shRNA) specifically silenced DLL4 in mice, which significantly inhibited the growth of transplanted tumors." (PMID 35096263, 2022). "In the tumor microenvironment, tumor secreted angiogenic factors such as VEGF can induce the expression of DLL4 in endothelial cells." (PMID 36071128, 2022). "Dll4 blockers can effectively resist tumor activity and be helpful for targeting both Dll4 and VEGF signaling pathways, presenting strong potential for RCC management." (PMID 35945960, 2022). "In vivo, DLL4 silencing inhibited the tumor formation ability of GCSPCs, with the authors resulting that DLL4 affects GCSPC stemness, altering their pathological behavior." (PMID 35406423, 2022). "Studies have confirmed that DLL4 expression is up-regulated in the tumor vasculature compared with normal vessels." (PMID 35846998, 2022). "Another approach is based on blockade of DLL4, using antibodies or Dll4-Fc moieties, which leads to a more arborized vasculature, paradoxically providing less effective vascularization with poor tumor perfusion." (PMID 35682918, 2022).
tumor (continued). "DLL4 is a critical factor in vascular maturation and tumor angiogenesis and plays a key role in VEGF signaling." (PMID 35681234, 2022). "DLL4 is an important regulator of tumor angiogenesis and cancer stem cells and is activated in a wide range of human cancers." (PMID 35332121, 2022). "As the specific ligand for Notch1 and Notch4, DLL4 expression is closely related to tumor angiogenesis and metastasis." (PMID 35846998, 2022). "Dll4 blockade, for example, promotes excessive tumor vessel growth consistent with a role for Dll4-Notch signaling in promoting EC commitment." (PMID 34692672, 2021). "This is relatively well investigated in HNSCC; in particular the expression of Jagged1 and -2 in endothelial cells/capillaries within the tumour tissue, or of DLL4." (PMID 34944837, 2021). "Navicixizumab (OMP-305B83) is an IgG-like BsAb that suppresses tumor vascularization by blocking both DLL4 and VEGF." (PMID 34922633, 2021). "The importance of DLL4 in tumor angiogenic processes is highlighted by the fact that silencing its expression leads to an inhibition of proliferation and migration of ECs." (PMID 33681228, 2021). "We first evaluated the expressions of NOTCH1 and DLL4 in UM-UC-1 and SCaBER microtumors using a live single cell biosensor, which was demonstrated in cancer cells, tumor organoids derived from patients, and tumor tissues." (PMID 34831307, 2021). "The role of p110α in tumor angiogenesis is mediated by several factors, such as the regulation of endothelial cell proliferation and the expression of delta-like protein 4 (DLL4)." (PMID 34916492, 2021). "DLL4 inhibitor, either alone or in combination with another DLL4 inhibitor or irinotecan, showed its therapeutic value in xenograft tumor models." (PMID 34638298, 2021). "Dll4-regulated tumor angiogenesis has inspired the development of anti-DLL4 antibodies, as well as their study in both preclinical and early clinical models." (PMID 34124039, 2021). "The Notch ligands DLL4 and Jag1 are the best characterized Notch pathway factors that have roles in tumor angiogenesis." (PMID 33681228, 2021). "For example, it has been reported that blocking the action of Notch ligands such as DLL4 by a recombinant antibody can block angiogenesis and tumor progression–what was attributed to inactivation of hyperactive Notch signaling in BrCa." (PMID 33430387, 2021). "Numerous studies have proved that after blocking Dll4, despite the increase in tumor angiogenesis, the structural defects and poor perfusion will aggravate the degree of ischemia and hypoxia of tumor cells, and effectively inhibited the growth of tumors." (PMID 34667158, 2021). "In this study, we proved that EERAC remarkably inhibited CRC through suppressing Notch/DLL4/Hes1 pathway, and further inhibited tumor angiogenesis." (PMID 34476005, 2021). "Other reported findings impart evidence that NOTCH1 and DLL4 were overexpressed within the tumor vasculature and upregulation of NOTCH/c-MYC activates the AKT pathway via PTEN phosphorylation; consequently, the NOTCH activation intensifies PI3K/mTOR activity." (PMID 34940041, 2021). "Antibodies targeting individual Notch receptors and ligands (i.e., JAG1, DLL4) have been developed, showing anti-tumor efficacy against different types of cancers in preclinical studies, with manageable toxicity profiles." (PMID 34439228, 2021). "A lot of studies have disclosed the expression of NOTCH components in tumor contexture, especially DLL4/NOTCH1, being upregulated by VEGF." (PMID 34940041, 2021). "Alternative strategies, such as the selective upregulation of DLL4 signaling with a soluble DLL4-Fc have also been explored to treat tumor angiogenesis." (PMID 34926282, 2021). "They observed that REGN421 alone is able to reduce tumor angiogenesis through the disruption of juxtacrine Dll4-Notch1 interactions between endothelial and tumor cells, but the effects are magnified by VEGF blockade." (PMID 35582386, 2021).
tumor (continued). "Notch ligand Delta-like 4 (DLL4) has been proved to be closely related with tumorigenesis and tumor angiogenesis." (PMID 34476005, 2021). "In summary, we provided the proof of concept for the role of ectopic DLL4 expression in human T-ALL and also solid data indicating that spleen is required for tumor development in a mouse model of DLL4-driven T-ALL." (PMID 33408769, 2021). "For example, mAbs has been used against human DLL4, MMGZ01 and H3L2 to disrupt DLL4-NOTCH1 signaling within tumor-associated endothelium." (PMID 34374886, 2021). "Intriguingly, tumor vasculature becomes disorganized and overgrown upon pharmacologic inhibition of DLL4, ultimately reducing overall tumor growth due to dysfunctional tumor angiogenesis." (PMID 33681228, 2021). "DLL4 is highly expressed in tumor ECs and its expression can be regulated by VEGF, bFGF, and by low oxygen conditions (hypoxia) through hypoxia-inducible factor 1α (HIF1α)." (PMID 33681228, 2021). "In ovarian tumour xenograft models, DLL-4 antibodies specific for the stroma reduced Notch signalling in the blood vessels and in tumour cells directly surrounding the blood vessels." (PMID 32575680, 2020). "If linc-OIP5 can regulate DLL4 by cooperating with certain pro-vascular maturation factors to promote VN, it will have some considerable implications for tumor targeting therapy." (PMID 32046779, 2020). "In particular, DLL4 was highly expressed in the vascular endothelium, as described in other tumor models, as well as in accompanying histiocytes." (PMID 31616059, 2020). "Notch receptor activation on endothelial cells occurs via an interaction with DLL-4 and Jagged-1 ligands expressed on tumour cells." (PMID 32575680, 2020). "The area densities of DLL4-positive tumor vessels were 0.40 ± 0.03% in vehicle, 0.24 ± 0.03% in irinotecan, 0.11 ± 0.02% in mABL001, and 0.05 ± 0.01% in the combination treatment group, respectively." (PMID 33383646, 2020). "We further constructed three novel SS.BN3IL2Rγ- congenic strains by introgressing varying segments of BN chromosome 3 into the parental SSIL2Rγ- strain to localize the role of SSIL2Rγ- DLL4 on tumor EPR effect with precision." (PMID 32373218, 2020). "The previously characterized CXM models of TME vascular heterogeneity, SSIL2Rγ- (DLL4-high) and SS.BN3IL2Rγ- (DLL4-low) 24, 25, were used to determine the impact of tumor vascular organization on TNP uptake, distribution, and PTT response." (PMID 32373218, 2020). "On the other hand, a larger Notch1 decoy, N11–24, recapitulated the effects of inhibiting either JAG1 or DLL4 or both, depending on the tumor microenvironment and in vitro angiogenesis model used." (PMID 32922403, 2020). "Tumor micro-environment with low DLL4 expression altered the geographic distribution of nanoparticles towards closer proximity with vasculature which improved efficacy of PTT in spite of lower overall TNP uptake." (PMID 32373218, 2020). "Similar to VEGFR-2 expression in tumor vessels, DLL4 expression was markedly reduced in tumor vessels compared to CD31 after treatment with mABL001 or the combination, rather than treatment with irinotecan alone." (PMID 33383646, 2020). "DLL4 is expressed by tumor endothelial cells to regulate tumor angiogenesis, and by some tumor cells to maintain cancer stemness." (PMID 33383646, 2020). "In the studies of other cancers, DLL4 was also closely related to the invasion and metastasis ability of some tumor cells." (PMID 32742191, 2020). "Antibodies targeting the ligand DLL4 are able to dysregulate angiogenesis of the tumor in endothelial cells." (PMID 32796631, 2020). "In summary, we demonstrate that DLL4 is an important component of the Notch signaling pathway and mediates tumor growth through self-renewal of tumor initiating cells and vascular development." (PMID 32373218, 2020).